CD4 (CD4 molecule)
Diseases named in the same sentence as CD4 in open-access papers (continued):
Sharing a sentence is not in itself a finding about the gene and the disease.
asthma (continued). "Frequencies of CD4+ T cells producing IL-10 as well as CD4+ T cells producing IL-13 was positively correlated with the duration of asthma (r = 0.44, P < .004 and r = 0.4, P < .01, resp)." (PMID 21197090, 2010). "In contrast, frequencies of CD4+ producing IFN-γ were significantly reduced in children with asthma compared to healthy subjects (P < .0001)." (PMID 21197090, 2010). "Our studies demonstrate that exposure of the mouse lung to real-world ambient PM directly induces several features of asthma, concomitant with the activation of an adaptive immune response characterized by the recruitment and activation of CD4+ T lymphocytes." (PMID 20061214, 2010). "First indications were observed in two studies that aimed at eliminating CD4+ T cells from mice with experimental asthma by using monoclonal antibodies, against CD4 or IL-2, respectively." (PMID 20976014, 2010). "A number of studies have shown the important role of activated memory CD4+ T cells as the main producer of Th2 cytokines in asthma and other atopic diseases." (PMID 21197090, 2010). "The percentage of CD4+/IL-13+ was significantly higher in severe asthma than in children with intermittent disease symptoms." (PMID 21197090, 2010). "An important role for CD4+CD25+FoxP3+Tregs to immune regulation of a variety of chronic inflammatory disease scenarios including asthma has been noted." (PMID 19769993, 2010). "Regarding CD4 and CD8 markers, the role of CD4+ T cells in the immunopathogenesis of asthma is well documented, though little is known about the role of CD8+ T cells." (PMID 19087256, 2008). "Prior studies have shown that CD4+T-cells are essential for the development of isocyanate induced asthma, and the latter study showed that CD8+T-cells are important for the induction of dermatitis." (PMID 17662138, 2007). "The two protocols with exercise in healthy subjects showed increased expression of CD25 on blood T-lymphocytes, and subjects with asthma showed a transient reduction in CD4+ lymphocytes after UFP exposure." (PMID 16393658, 2006). "Asthma is characterized by chronic inflammation in the airways and the presence of a predominance of CD4+ T-helper 2 (Th2) cells that secrete interleukin (IL)-4, IL-5, and IL-13 cytokines." (PMID 17185285, 2006). "The sensitivity of CD4+ T cells to various MAPK inhibitors prompted us to analyze these compounds in an animal model of asthma." (PMID 15833106, 2005). "By using CD4+ T lymphocytes, ex vivo transduced to express IL-10, it was shown that allergen-specific lymphocytes can suppress allergen-induced asthma manifestations via production of IL-10." (PMID 15538945, 2004). "Significantly higher levels of soluble IL-2R and soluble CD4 were found in patients with asthma compared with the control group." (PMID 18475650, 1995). "Virus-induced asthma exacerbations appear to involve not only the upregulation of Th2 cytokines but also an increased expression of receptors, particularly IL-4Rα, in both epithelial and CD4 + T helper cells." (PMID 41576028, 2026). "Myeloid-derived regulatory cells (MDRCs) control CD4+ T cell responses in asthma." (PMID 42192147, 2026). "However, the frequency of CD62L+ ILC2s was higher, and CD4+ KLRG1+ cells among TCM cells was lower only in T2 subjects with asthma." (PMID 40965120, 2025). "Concurrently, Sema3E KO mice that were subjected to the type-2 low asthma model demonstrated an elevated presence of pulmonary neutrophils, dendritic cells, CD4 T cells, as well as increased levels of IL-17, TNF, IL-1β, CXCL-8, and MCP-1/CCL2 in comparison to their WT counterparts." (PMID 40512736, 2025). "Upregulated miR-21 and miR-126 promoted Th2 differentiation of CD4+T cells during asthma." (PMID 39867638, 2025). "Therefore, to identify the T cell subset predominantly involved in asthma pathogenesis, we selectively depleted CD4+ or CD8+ T cells in C57BL/6 mice challenged with HDM." (PMID 40226621, 2025).
asthma (continued). "Asthma also demonstrated heterogeneous associations with B cells (FDR = 0.010), CD4 T cells (FDR = 0.010), DC1 (FDR = 0.010), DC2 (FDR = 0.010), and proliferating T cells (FDR = 0.025), with the latter additionally showing heterogeneity in its association with IPF (FDR = 0.016)." (PMID 41463538, 2025). "The intricate interplay between LIGHT-HVEM-BTLA signaling on CD4+ T cells may play a crucial role in the development of severe steroid-resistant asthma in BXD75 mice." (PMID 40226621, 2025). "Similarly, the expression of NEAT1 is significantly upregulated in CD4+ T cells in the peripheral blood of children with asthma." (PMID 40362651, 2025). "Consequently, asthma symptoms are exacerbated by the promotion of an increase in CD4+ Th2 cells and the further secretion of cytokines, such as IL-4, IL-5, and IL-13." (PMID 41155294, 2025). "The mechanistic basis for failure to induce IL-10 production in the CD4+ T cells of individuals with asthma may be attributable to the favored expression of the cytoplasmic (cyt) tail isoform of CD46." (PMID 40309766, 2025). "Therefore, SDCBP plays a dual role in asthma by promoting memory CD4 T cell responses while limiting activated CD8 T cell activity." (PMID 40634444, 2025). "A higher frequency of CD4+ CRTH2+ T memory cells was associated with T2 features independent of asthma status." (PMID 40965120, 2025). "Asthma samples showed elevated levels of monocytes, macrophages, neutrophils, and nTreg cells, while the control group had higher levels of NK cells, CD4+ T cells, CD8+ T cells, gamma-delta T cells, iTreg cells, Th2 cells, Tfh cells, exhausted T cells, and effector memory T cells." (PMID 40165005, 2025). "We observed systemic immune perturbations in some patients, including recurrent infections, markedly elevated serum IgE, CD4+ T-cell memory skewing, and asthma, suggesting that chronic skin barrier disruption may contribute to secondary immune dysregulation." (PMID 41346588, 2025). "Herein, we first evaluated the expression levels of CD226 on CD4+ T cells in patients with asthma." (PMID 39349422, 2024). "Sialostatin L, a cysteine protease inhibitor from tick saliva, shows multifunctional effects on the immune system, which not only inhibits the percentage of CD4+ cells but also reduces the production of IL-9 from Th9 cells in an OVA-induced experimental asthma." (PMID 38444844, 2024). "CD4+ T cells are the main determinant of the inflammatory phenotype of asthma." (PMID 39611173, 2024). "Treatment with anti-CD3 can significantly inhibit the proliferation of CD4+ T cells in the peripheral blood of patients with AS and, in mice, anti-CD3 treatment was observed to inhibit CD4+ T-cell activity in lung tissue and blood vessels, significantly reducing the level of asthma inflammation." (PMID 38812518, 2024). "However, due to the small number of participants, we were unable to assess CD46 expression on CD4+ T cells in patients with severe asthma (n = 3)." (PMID 39403120, 2024). "Asthma is a chronic airway inflammatory disease in which CD4+ T cell dysregulation occurs." (PMID 39349422, 2024). "We speculated that circulating palmitoylcarnitine may induce apoptosis of certain subtypes of CD4+ T cells and human bronchial epithelial cells, leading to the occurrence of asthma." (PMID 38378549, 2024). "To identify ILC2-specific SEs, we performed H3K27ac chromatin immunoprecipitation sequencing (ChIP-seq) of lung ILC2s, defined as Lin−CD45+Thy1+ST2+ cells, and lung CD4 T cells in house dust mite-induced asthma models, which recapitulate activated ILC2s and activated Th2 cells in vivo, respectively." (PMID 38969652, 2024). "The interaction between cytokines and CD4+ T cells contributes to the progression of severe asthma." (PMID 38378549, 2024). "Furthermore, overexpression of PLZFin vitro significantly increased the number of CD4+ TRMs, likely leading to asthma exacerbation." (PMID 39632661, 2024).
asthma (continued). "It has also been shown that SEMA4A-Plexin-D1 contributed to the elevated IL-4 and IL-17 in patients with systemic sclerosis (SSc), and the same manner can be seen for other T CD4+ mediate diseases, including asthma, rheumatoid arthritis (RA), and multiple sclerosis (MS)." (PMID 38148815, 2024). "This study aimed to investigate the role of CD4+ TRMs in immune tolerance via asthma models." (PMID 39632661, 2024). "Direct examination of bronchial tissue by endobronchial biopsy has demonstrated distinct patterns of inflammatory cell recruitment in stable asthma and COPD, i.e., a predominance of CD4+ T cells and eosinophils in asthma and CD8+ T cells and macrophages in COPD." (PMID 39598462, 2024). "Further research is imperative to uncover alternative pathways through which pDCs might influence CD4+ T cell reactions in asthma." (PMID 39530090, 2024). "To identify specific regulatory elements within the hG900 region in CD4+ T cells, we analyzed publicly available datasets of chromatin immunoprecipitation sequencing (ChIP-seq) of peripheral blood CD4+ T cell subsets obtained from individuals with asthma." (PMID 38923989, 2024). "Moreover, Qiu Yu-Ying and collaborators found that CD4+ T cells from patients with asthma presented both an up-regulation of miR-145-5p and a down-regulation of Runt-related transcription factor 3 (RUNX3) expression compared with healthy controls." (PMID 38337625, 2024). "When suitable ligands are used to selectively target the transcription factor PLZF in CD4+ TRMs, new targeted drugs may be discovered, which provides broad prospects for the clinical development of asthma treatments." (PMID 39632661, 2024). "Then, the CD4 + T cells were isolated from peripheral blood and spleen in asthma and control mice." (PMID 39342146, 2024). "DNA‐PKcs regulates the CD4+ T cells differentiation into Th1 and Th2 cells by Gata3 and Tbet in asthma, whether the similar mechanisms exist in other diseases remains to be explored." (PMID 38898995, 2024). "To determine if AR signaling in CD4+ T cells attenuated allergen-induced airway hyperresponsiveness (AHR) to methacholine, a physiological hallmark of asthma, we measured airway resistance in response to increasing concentrations of nebulized methacholine via Flexivent." (PMID 39404231, 2024). "It was also reported that aerobic glycolysis is increased in CD4 T cells in asthma." (PMID 38629073, 2024). "Furthermore, circ_0005519 expression markedly elevated within CD4+ T cells and PBMCs from 30 asthma patients in comparison with 24 normal subjects, and the upregulation was correlated with the exhaled nitric oxide level." (PMID 39239069, 2024). "Moreover, we downloaded the gene expression profile from the GEO database using data from PBMCs, peripheral blood CD4+ T cells and Th2 cells from patients with asthma or healthy subjects." (PMID 39349422, 2024). "The transcription factor PLZF could facilitate the development of CD4+ TRMs, providing a novel and promising therapeutic target for asthma." (PMID 39632661, 2024). "The massive IL-18 and IL-1β release from pyroptotic AECs and macrophages may influence the differentiation, proliferation and function of CD4+ T cells, and determine the course of asthma progression." (PMID 39611173, 2024). "Despite this, CD4+ T-cells are under-represented in asthma transcriptome studies." (PMID 38129444, 2023). "To date, only one other transcriptome study on asthma focused on CD4+ T cells." (PMID 38129444, 2023). "CD4+ T cells play a central role in the pathogenesis of asthma." (PMID 38029078, 2023). "Notably, we found that the expression of IFT20 was increased in CD4+ T cells from patients suffering from asthma relative to those from healthy subjects (Gene Expression Omnibus (GEO) accession number GSE75011)." (PMID 37029318, 2023). "The pathogenesis of asthma is mainly due to a disparity in the polarization of CD4+ Th cells." (PMID 37623736, 2023).
asthma (continued). "As well, this circumstance also has been described in asthma patients, where some interleukins have been found raised, such as IL6, IL-4, IL-5, and IL-13, secreted from CD4+ lymphocytes, promoting an allergic inflammation which involves a worse prognosis of asthma disease." (PMID 37920579, 2023). "Activated CD4+ T cells are divided into two subsets—T regulatory (Treg) and T effector (Teff) cells (Th1/Th2/Th17) with the former playing an immune regulatory role and the latter driving asthma pathogenesis and determining the asthmatic phenotype." (PMID 38029078, 2023). "Furthermore, the relative protein level of ROR-γT in spleen CD4+ T cells increased in severe asthma but decreased after miR-146a-3p agomir was inhaled." (PMID 36961677, 2023). "GliSODin® abrogates asthma features and reduces CD4+ T-cell polarization and reactivation." (PMID 37346413, 2023). "It is therefore widely recognised that CD4+ T-cells play an important role in asthma pathogenesis." (PMID 38129444, 2023). "Thus, the CC011 strain provides a new mouse model of T2-high, severe asthma driven by natural genetic variation likely acting through CD4+ T-cells." (PMID 37296458, 2023). "In human asthma-associated CD4 T cells, SPI1 (the gene encoding PU.1) is notably not upregulated in Th2 cells, even when analysis is focused on those cells producing IL-9." (PMID 37163370, 2023). "Among the 22 types of immune cells, CD4 + T cells, B cells, and mast cells showed significant differences between the two groups, which is consistent with previous reports on immune cell migration and infiltration in asthma." (PMID 37259023, 2023). "The lowest median proportion of PD1 + CD4 + or PD1 + CD8 + cells was found in patients with asthma." (PMID 37535195, 2023). "CD8+ T cells are known for the role they play in immune tolerance, and they are a good source of proinflammatory cytokines in asthma CD4+ cells and the ratio of CD4+/CD8+ cells (a marker of chronic lung disease) are lower in males than females throughout adulthood." (PMID 35769576, 2022). "Moreover, the mixed‐granulocytic endotype, characterized by elevated levels of eosinophils and neutrophils in bronchial‐alveolar lavages, involves the induction of dual IL‐17 and IL‐4‐secreting CD4+ T‐cells in some patients with severe asthma." (PMID 35734271, 2022). "Allergic asthma caused by exposure to allergens is observed when DCs react to the recognition of allergens and induction of differentiation of naïve CD4+ T cells into Th2 and Th17 cells, thereby promoting or inducing the secretion of factors that induce asthma." (PMID 36139376, 2022). "In asthma, a significant correlation of disease duration with the redistribution of receptors on the tested immune cells was demonstrated and was most pronounced for monocytes, naïve CD4+ cells, and cytotoxic T lymphocytes." (PMID 36611799, 2022). "Moreover, children with more MAIT cells at 1 year of age were less likely to develop asthma accompanying by IFN-γ-producing CD4+T cells by 7 years of age." (PMID 36458017, 2022). "CD4+ T cells play an important role in the pathophysiology of asthma." (PMID 35801505, 2022). "Biased differentiation of CD4+ T cells contributes to abnormal inflammation in asthma." (PMID 35769905, 2022). "Given the functional relationship between Foxa2 and Shh, the opposing roles of Shh and Foxa2 in allergic asthma, the role of Hh in driving Th2 differentiation, and the importance of CD4+ Th2 responses in amplifying asthma, we investigated the function of Foxa2 in CD4 T-cells in AAD." (PMID 36003391, 2022). "Thus, it is necessary to discuss the role of CD4+ T cells during stable asthma and asthma exacerbation separately." (PMID 36032162, 2022). "Overall, these data imply that future strategies might need to separately target existing Trm cells as well as circulatory memory T cells to fully inhibit CD4 T cell reactivity to airborne allergens and to fully limit exacerbations of asthma." (PMID 35936001, 2022).
asthma (continued). "In peripheral blood of patients with allergy and asthma, allergen-specific CD4+ T cells secreted IL-9, which was significantly reduced after successful immunotherapy, suggesting that IL-9 was an important secreted product of long-term stimulation of allergenic T cells." (PMID 36524132, 2022). "In contrast, T2 specifically expressed CD4, supposed to be CD4+ T cell, which may play an indispensable role in the inflammatory responses in asthma." (PMID 36439114, 2022). "Even though the expression of Shh by airway epithelium encourages the Th2 differentiation of CD4 T-cell, the allergic response might be exacerbated in a dust mite-induced asthma model." (PMID 35681469, 2022). "In addition, the regulatory network among circHIPK3, LncGAS5 and miR-495 can promote Th2 differentiation in allergic rhinitis, and hsa_circ_0002594 and hsa_circ_0005519 can affect asthma by regulating CD4+ T cells." (PMID 35693804, 2022). "Analysis of these CD4+ expressing subsets showed that smoking in the asthma group, but not the healthy group, associated with significantly increased blood frequencies of CD4+CD45RO+ILC3s." (PMID 35789151, 2022). "The genome-wide mapping of histone modifications in CD4 memory as well as TH1 and TH2 cells revealed differential enrichment of dimethylated lysine 4 of histone H3 (H3K4me2) in TH2 enhancers associated with susceptibility to asthma." (PMID 35163689, 2022). "ARRB2, well known to regulate G protein-coupled receptor function and receptor internalization, has been also recognized as an important pro-inflammatory mediator by promoting CD4+ T cells migration, Th2 cell chemotaxis, and inflammatory cytokine production in asthma." (PMID 35958620, 2022). "Examples of significant associations between adult cell types and diseases include Graves’ disease, hypothyroidism, Hashimoto’s thyroiditis, and pediatric asthma, and all of which were significantly associated with immune-related cells such as T lymphocyte 1 (CD8) and T lymphocyte 2 (CD4)." (PMID 36232752, 2022). "Similarly, an evaluation of the change in IL-10 expressed through CD4+ regulatory T cells in the serum shows a 60% reduction in asthma induced by OVA compared to that in normal mice." (PMID 36115955, 2022). "Upregulation of Hsa_circ_0005519 could inhibit the expression of has-let-7a-5p in CD4 T cells of asthmatic patients and promote the production of IL-13 and IL-6, thereby exacerbating asthma." (PMID 35586697, 2022). "CD4 + helper T (Th) cell subsets are critically involved in the pathogenesis of asthma." (PMID 35898499, 2022). "The expression levels of CD3+ lymphocyte subsets were similar among the recurrent infection group, the asthma group, and the control group (P>0.05), and there were statistically significant differences in CD4+, CD8+ and CD4+/CD8+ lymphocyte subsets among the three groups (P<0.05)." (PMID 35991273, 2022). "As the disease progression pattern and asthma treatment options differ depending on the differentiation of CD4+ T cells, elucidating the biological roles of CD4+ T cells in the pathogenesis of asthma is critical for developing effective asthma treatments and predicting patient prognosis." (PMID 34769255, 2021). "In CD4+ T cells, the IL-33/ST2 signaling pathway plays an important role in Th2 activation, and interestingly, IL1RL1 variants are linked to increased risk of IL-33-driven type 2 inflammation in asthma." (PMID 33924911, 2021). "Two asthma phenotypes have been described, Th2 and non-Th2, which are determined by CD4+ T cells." (PMID 34769255, 2021). "Our results demonstrated that Spry2 in CD4+ T cells is indispensable for the asthma phenotype." (PMID 33684096, 2021). "CD4+T helper (Th) cells are important mediators of immune responses in asthma and cancer." (PMID 33748292, 2021). "In the Placebo group the count of CD3+, CD45+ and CD3+CD4+ decreased, that may be related to more frequent infections that have led to asthma exacerbations in these patients (described in our previous study)." (PMID 33472687, 2021).